TLL1 (tolloid like 1)
Description:
Protease which processes procollagen C-propeptides, such as chordin, pro-biglycan and pro-lysyl oxidase. Required for the embryonic development. Predominant protease, which in the development, influences dorsal-ventral patterning and skeletogenesis.
Synonyms: TLL; ASD6
Tractability: Small molecule: a high-quality ligand is known. Antibody: UniProt places it where antibodies can reach, with high confidence; its Gene Ontology location is reachable by antibodies, with high confidence; UniProt predicts a signal peptide or a membrane-spanning region. PROTAC: ubiquitination databases record sites on it; a small molecule that binds it is known.
Target class: Enzyme; Hydrolase
Gene: Protein-coding gene on chromosome 4 (165,873,237 to 166,104,457, forward strand). Ensembl gene ENSG00000038295.
Subcellular location: Secreted
Subcellular location (Human Protein Atlas): Vesicles; Predicted to be secreted
Pathways (Reactome):
Extracellular matrix organization: Anchoring fibril formation; Collagen biosynthesis and modifying enzymes; Crosslinking of collagen fibrils; Degradation of the extracellular matrix
Gene Ontology:
Molecular function: metalloendopeptidase activity; serine-type endopeptidase activity; calcium ion binding; metallopeptidase activity; zinc ion binding
Biological process: collagen fibril organization; dorsal/ventral pattern formation; protein processing; skeletal system development; proteolysis
Cellular component: extracellular region
Genetic constraint (gnomAD): Loss-of-function variants: 42 observed, 116.42 expected, observed/expected ratio (o/e) 0.36, 90% interval 0.28 to 0.47. The upper end of that interval is the gene's LOEUF score, 0.47, which puts it in group 2 of 6, group 1 being the genes least tolerant of losing a copy. Missense variants: 1,089 observed, 1,257.9 expected, observed/expected ratio (o/e) 0.87, 90% interval 0.82 to 0.91. Synonymous variants: 440 observed, 430.1 expected, observed/expected ratio (o/e) 1.02, 90% interval 0.94 to 1.11.
Gene-disease validity (ClinGen):
ClinGen rates the evidence that TLL1 causes each of these diseases.
congenital heart disease (autosomal dominant): Limited. A heart disease that is present at birth.
Homologues: Orthologues: chimpanzee TLL1 (99% identical), macaque TLL1 (99% identical), dog TLL1 (95% identical), pig TLL1 (95% identical), mouse Tll1 (94% identical), rat Tll1 (94% identical), guinea pig TLL1 (88% identical), tropical clawed frog tll1 (85% identical), zebrafish tll1 (82% identical), rabbit TLL1 (72% identical), Drosophila melanogaster tld (42% identical). Paralogues in human: TLL2 (72% identical), BMP1 (71% identical), CUBN (18% identical), CNTNAP2 (15% identical), CNTNAP4 (15% identical), CNTNAP3 (14% identical), CNTNAP3B (14% identical), CNTNAP5 (14% identical), CNTNAP1 (13% identical), F8 (13% identical), F5 (12% identical), MEP1B (12% identical), and 23 more.
Diseases named in the same sentence as TLL1 in open-access papers:
TLL1 is named in the same sentence as 26 diseases in open-access papers, as found by Europe PMC text mining. Sharing a sentence is not in itself a finding about the gene and the disease. The quoted sentences say what the papers report.
hepatocellular carcinoma (6 papers, 2020 to 2025). A malignant tumor that arises from hepatocytes. "The TLL-1 intronic variant rs17047200 (A > T) was described, for the first time, in 2017 as associated with development of hepatocellular carcinoma after eradication of hepatitis C virus infection." (PMID 34249902, 2021). "While TLL1 is known to be necessary for normal septation and positioning of the heart, a more recent report found that it is associated with the development of hepatocellular carcinoma after the eradication of HCV." (PMID 39746113, 2025). "In hepatocellular carcinoma, SNP may impact the splicing of TLL1 mRNA and result in short variants with high catalytic activity, speeding up the development of liver fibrosis and cancer." (PMID 37388244, 2023). "In a GWAS, a research group declared the association between the TLL1 rs17047200 SNP and hepatocellular carcinoma pathogenesis and found elevated TLL1/TLL1 mRNA in animal models of liver injury and human liver tissues with fibrosis, in comparison with controls." (PMID 34071309, 2021). "One GWAs in 456 Japanese patients with chronic hepatitis C identified TLL1 as a novel susceptibility locus for hepatocellular carcinoma (HCC) after HCV clearance following interferon- based treatment." (PMID 39201329, 2024).
atrial septal defect (4 papers, 2019 to 2023). Interauricular communication is a congenital malformation characterized by a communication between the atrial chambers of the heart. "In our previous work, we linked mutations in TLL1 to human atrial-septal defect 6 (ASD6) (OMIM 613087)." (PMID 30538173, 2019). "Heterozygous mutations in the TLL1 gene are responsible for atrial septal defect (ASD6)." (PMID 36980952, 2023). "Alternatively, these haplotypes could also host mutations that affect lamb survival in a later growth period, as observed for heart malformation in mouse and in humans (“atrial septal defect 6” [ASD6, OMIM #613087];) associated with the TLL1 gene located in the LDHH7 region." (PMID 33932977, 2021). "Inactive mammalian tolloid-like 1 (tll1) and mutations detected in tolloid-like 1 (TLL1) have been linked to the lack of the heart septa formation in mice and to a similar human inborn condition called atrial-septal defect 6 (ASD6; OMIM 613087, formerly ASD II)." (PMID 30538173, 2019).
COVID-19 (3 papers, 2021 to 2022). A disease caused by infection with severe acute respiratory syndrome coronavirus 2. "The C and A alleles of SNPs IFN-λ rs12979860, TLL1 rs17047200 correlate with the severity of COVID-19, where the AG genotype of the DDR1 rs4618569 variant are associated with severe COVID-19 cases and poor outcomes." (PMID 34071309, 2021). "Methods: 141 COVID-19 positive patients and 100 healthy controls were tested for interferon-lambda-3 rs12979860, TLL1 rs17047200 and DDR1 rs4618569 polymorphism by TaqMan probe-based genotyping." (PMID 34071309, 2021). "In the AA genotype of TLL1 rs17047200, COVID-19 was severe in 36 (38.3%) cases compared to 16 (43.2%) cases in the TA genotype and 7 (70%) cases in the TT genotype, with p = 0.152." (PMID 34071309, 2021). "The CC genotype of rs12979860 cytokine, the AA genotype of TLL1 rs17047200 and the AA genotype of the rs4618569 variant of DDR1 showed a higher incidence of COVID-19 compared to the others." (PMID 34071309, 2021). "Another enzyme involved in the COVID-19 development is Tolloid-likeprotein 1 (TLL1)." (PMID 35062298, 2022).
chronic hepatitis C (2 papers, 2018 to 2020). "Considering recent evidence that TLL1 rs17047200 is a novel risk variant for fibrosis progression and liver cancer in patients with chronic hepatitis C, we examined its potential role in MAFLD." (PMID 33306709, 2020). "A recent genome-wide study in Japanese patients with chronic hepatitis C identified the TLL1 rs17047200 single nucleotide polymorphism (or other intronic variants in strong LD), as a novel risk variant for HCC, indirectly via regulating liver fibrosis." (PMID 33306709, 2020).
Hepatic fibrosis (2 papers, 2020 to 2023). The presence of excessive fibrous connective tissue in the liver. "A recent small study of Japanese patients with MAFLD (n = 258) has suggested that the TLL1 rs17047200 T allele is associated with advanced liver fibrosis (p = 0.044)." (PMID 33306709, 2020). "We investigated the association of the TLL1 rs17047200 polymorphism with liver fibrosis in a cohort of Caucasian patients with MAFLD (n = 728)." (PMID 33306709, 2020). "In total, the findings suggest that the TLL1 rs17047200 genetic variant is either not a common genetic marker for liver fibrosis across different etiologies or alternatively that rs17047200 is unlikely to be the causative variant in Caucasian patients." (PMID 33306709, 2020). "However, TLL1 is likely involved in the pathogenesis of liver fibrosis." (PMID 33306709, 2020). "However, TLL1 could be involved in the pathogenesis of liver fibrosis." (PMID 33306709, 2020).
hepatitis C virus infection (2 papers, 2020 to 2021). A viral infection caused by the hepatitis C virus. "Genome-wide association studies have found that TLL1 variants are associated with HCC after hepatitis C virus infection eradication." (PMID 33072579, 2020).
liver disease (2 papers, 2018 to 2025). "We concluded that TLL-1 genetic variants determined fibrotic improvement in CHC with curative antivirals, particularly in patients with mild liver disease." (PMID 30305682, 2018). "However, among patients with mild liver disease (F0-2), the proportion of fibrosis improvement was significantly higher in those with the TLL-1 rs17047200 AA genotype compared to those with a non-AA genotype at (33.3% vs. 0%, p = 0.005)." (PMID 30305682, 2018).
breast carcinoma (1 paper, 2013). "In parallel studies for downregulated genes, we were able to identify seven genes with mutations in colon cancer (DPP10, PCSK2, ADAM33, RELN, CAPN13, ADAMTS1 and ADAMTS15), and five genes with mutations in breast carcinomas (MASP3, ABHD12B, TLL1, CPA3 and DPP6)." (PMID 24243807, 2013).
epilepsy (1 paper, 2021). A brain disorder characterized by episodes of abnormally increased neuronal discharge resulting in transient episodes of sensory or motor neurological dysfunction, or psychic dysfunction. "Tll1, dopamine receptor D2 (Drd2) and cluster of differentiation 200 (Cd200) were selected because of their reported link to epilepsy, shared interactions and molecular functions." (PMID 33584828, 2021).
glaucoma (1 paper, 2021). Increased pressure in the eyeball due to obstruction of the outflow of aqueous humor. "TLL1 and SULF1 have no reported associations with glaucoma or IOP regulation, however, both genes encode proteins associated with fibrosis and an epithelial to mesenchymal transition (EMT) which shows similar phenotypic changes to that observed in POAG." (PMID 34440692, 2021).
schizophrenia (1 paper, 2011). A major psychotic disorder characterized by abnormalities in the perception or expression of reality. "We examined the association between schizophrenia and the neuropilin and tolloid-like 1 gene (NETO1)." (PMID 22205981, 2011).
status epilepticus (1 paper, 2017). Status epilepticus is defined as a continuous seizure lasting more than 30 min, or two or more seizures without full recovery of consciousness between any of them. "Real-time PCR analysis showed the expected higher levels of Arc, FosB, Inhba, Npas4, Pchd8 and Tll1 bound to Upf1 after status epilepticus whereas levels of Slc1a2 were not different between groups." (PMID 28128343, 2017).
steatosis (1 paper, 2020). Increased lipid within the cytoplasm of cells. "As we demonstrate, the TLL1 rs17047200 variant did not influence any histological parameter (steatosis, inflammation or fibrosis) in our large cohort of Caucasian patients." (PMID 33306709, 2020).
type 2 diabetes (1 paper, 2012). "The significantly associated genetic variants in the DDAH1IL18 and TLL1 genes will need to be explored in other ethnic groups, and in larger cohorts of individuals with type 2 diabetes and cardiac disease." (PMID 22533709, 2012).
cancer (7 papers, 2017 to 2025). A tumor composed of atypical neoplastic, often pleomorphic cells that invade other tissues. "We also identified the top 1 GEAR in individual cancer types, such as TLL1 (BLCA), PGK1 (BRCA), RFXANK (CESC), DPP7 (COAD), VWA8 (KIRC), SCMH1 (LGG), HILPDA (LIHC), TLE1 (LUAD), CD151 (LUSC), ANKRD13A (OV), SOCS2 (PAAD), DRG2 (PRAD), ADAMTS6 (STAD), PSMB8 (THCA), ASS1 (UCEC)." (PMID 41404730, 2025). "MMP17, PI3, TLL1, ANGPTL4, and TGFBI have all been previously associated with cancer." (PMID 37388244, 2023). "Both enzymes (TLL1 and TLL2) play a role in tissue remodeling and are upregulated in diverse human diseases, including chronic inflammatory disorders and cancer." (PMID 38396603, 2024). "A luciferase assay found that TLL1 isoforms, depending on the types of its isoforms, regulate differently the maturation of TGF-β (transforming growth factor β), which is known to play important roles in cancer progression." (PMID 39746113, 2025).
tumour (5 papers, 2017 to 2023). "The expression levels of TLL1, HMCN2, FREM2 and MMP17 were significantly higher in normal ovarian tissues than in tumour tissues." (PMID 37388244, 2023). "In each case we confirm the profile observed, with TLL1 and ZNF350 being more methylated in the tumour than placenta." (PMID 31357948, 2019). "Low-coverage WGR of individuals showing tumor regression and those that succumbed to the disease enabled a genome-wide association study to be undertaken, which identified two genomic regions that may be associated with resistance to DFTD including PAX3 and TLL1 loci." (PMID 31717707, 2019).
TLL1 also shares sentences with these, for which no sentence is quoted: asthma (1 paper); cardiac disease (1); colon cancer (1); fatty liver disease (1); fibrosis (1); infection (1); leukemia (1); liver cancer (1); neurodevelopmental disorder (1); serous ovarian carcinoma (1).